TMEM269 (transmembrane protein 269)
Gene: Protein-coding gene on chromosome 1 (42,784,991 to 42,816,619, forward strand). Ensembl gene ENSG00000274386.
Subcellular location: Membrane
Gene Ontology:
Cellular component: membrane
Genetic constraint (gnomAD): Loss-of-function variants: 17 observed, 20.39 expected, observed/expected ratio (o/e) 0.83, 90% interval 0.57 to 1.25. The upper end of that interval is the gene's LOEUF score, 1.25, which puts it in group 5 of 6, group 1 being the genes least tolerant of losing a copy. Missense variants: 211 observed, 255.47 expected, observed/expected ratio (o/e) 0.83, 90% interval 0.74 to 0.93. Synonymous variants: 93 observed, 101.99 expected, observed/expected ratio (o/e) 0.91, 90% interval 0.77 to 1.08.
Homologues: Orthologues: rabbit TMEM269 (78% identical).